CD47 (CD47 molecule)
Diseases named in the same sentence as CD47 in open-access papers (continued):
Sharing a sentence is not in itself a finding about the gene and the disease.
multiple sclerosis (9 papers, 2010 to 2024). A progressive autoimmune disorder affecting the central nervous system resulting in demyelination. "Dysregulation in both C1q and CD47 have been implicated in age-related diseases such as Multiple Sclerosis (MS), a chronic demyelinating disease, synapse removal, and normal aging." (PMID 39399501, 2024). "Both C1q and CD47 have been implicated in Multiple Sclerosis, a demyelinating disease, but whether they play a role in age-related myelin pathology is currently unknown." (PMID 39399501, 2024). "The present review attempts to summarize the role of CD47 and its associated receptor SIRPα (signal regulatory protein α) during the development of neurodegenerative disorders such as Multiple Sclerosis, Stroke, Parkinson’s, Alzheimer and traumatic brain injury among others." (PMID 34203368, 2021). "In the present review, we have highlighted the current evidence regarding the importance of CD47/ SIRPα in pathologies like stroke, Multiple Sclerosis, Alzheimer’s, spinal cord injuries, TBI, and Parkinson’s." (PMID 34203368, 2021). "For example, Junker's group showed that three microRNAs, namely, miRNA-34a, miRNA-155 and miRNA-326, when up-regulated in active multiple sclerosis lesions, target the 3ʹ-untranslated region of CD47 and reduce CD47 in brain resident cells." (PMID 34093795, 2021). "Recent studies show that CD47 is downregulated within multiple sclerosis brain lesions and that myelin phagocytosis in enhanced by blocking CD47." (PMID 28545141, 2017). "The immunoregulatory role of CD47 is emphasised in human disease because this NIReg is lost at the edge of a demyelinating plaque in multiple sclerosis, removing the immunoregulation of local microglia and increasing disease progression." (PMID 21152121, 2010). "The down regulation of the expression of NIRegs, CD200 and CD47, promotes microglial activity as found in demyelinating plaques from cases of multiple sclerosis." (PMID 21152121, 2010). "For example, CD47 levels have been found to be low in active lesions in multiple sclerosis, hinting that increasing CD47 in these regions might ameliorate neuroinflammation." (PMID 34197341, 2021). "In this aspect, both CD47 and SIRP receptors have been implied in the development of neurodegenerative pathologies and processes such as neuroinflammation, multiple sclerosis, Alzheimer’s, Stroke, spinal cord injuries among others." (PMID 34203368, 2021). "Thus, it may be useful to consider targeting SIRPα-CD47 interaction to accelerate the removal of myelin debris in Wallerian degeneration and additional pathologies of the nervous system in which myelin breaks down and impedes healing (e.g., multiple sclerosis)." (PMID 31883525, 2019).
myeloid leukemia (9 papers, 2012 to 2025). A clonal proliferation of myeloid cells and their precursors in the bone marrow, peripheral blood, and spleen. "More recently, an enhanced expression of CD47 has been reported for murine myeloid leukemias, as well as human normal and leukemic hematopoietic stem cells and many human solid tumors, and that increased CD47 expression is associated with reduced patient survival in AML and solid tumors." (PMID 23401787, 2013). "With CD47 being a transmembrane protein expressed on the surface of tissue cells and myeloid leukemia cells, CD47 serves as a self-marker for host tissue recognition and evasion of immune response." (PMID 34638574, 2021). "CD47 seems to be over expressed in myeloid malignancies, and overexpression of CD47 in myeloid leukemia increases its pathogenicity by allowing for tumor evasion of macrophages." (PMID 34639121, 2021).
pulmonary fibrosis (9 papers, 2020 to 2025). Chronic progressive interstitial lung disorder characterized by the replacement of the lung tissue by connective tissue, leading to progressive dyspnea, respiratory failure, or right heart failure. "However, the molecular details of how JUN caused, or CD47 blockade disrupted, the development of lung fibrosis and the implications for human pulmonary fibrosis diseases remained unknown." (PMID 32493933, 2020). "Surprisingly, they identified that blockade of PD-L1, CD47, and IL-6 significantly alleviated the severity of pulmonary fibrosis not only in bleomycin-induced pulmonary fibrosis mice model but in IL-6 knockout and humanized NSG mice models." (PMID 36544757, 2022). "We tested blockade of PD-1/PD-L1 (single/combined with anti-CD47 antibody) in the mouse model of lung fibrosis mediated by bleomycin in which we had initiated treatment at day 4 after fibrosis induction as a semi-therapeutic approach." (PMID 32493933, 2020). "In the same study, we also found that the PD-L1 is upregulated in murine lung fibrosis in a subset of pro-fibrotic fibroblasts (in both the genetic and bleomycin chemical-injury models), which highly co-expressed CD47." (PMID 32493933, 2020). "Although there was increased PD-L1 co-expression with FSP1 in untreated mice with lung fibrosis, we found significantly decreased PD-L1+CD47+ fibroblasts." (PMID 32493933, 2020). "In this paper, we have made the intriguing observations that two critical immune checkpoint proteins-CD47 and PD-L1-are not only induced in a mouse model of lung fibrosis, but also in lung fibroblasts of human pulmonary fibrosis." (PMID 32493933, 2020). "Notably, combined immunotherapy with CD47- and IL-6-blocking agents has been shown to reverse fibrotic conditions in mice, suggesting new therapeutic alternatives for treating pulmonary fibrosis." (PMID 36842152, 2023). "In a mouse model of bleomycin-induced pulmonary fibrosis, we observed that treatment with the CD47 inhibitor RRx-001, at a dose of 10 mg/kg for a duration of 2 weeks, significantly reduced ROS production in lung sections of mice exposed to bleomycin, as measured by the fluorescence of DHE." (PMID 38136144, 2023). "Therefore, future studies investigating the contribution of TSP-1 to fibroblast activation and pulmonary fibrosis should consider the involvement of TSP-1 receptors other than CD47." (PMID 38136144, 2023). "Meanwhile, the preclinical study demonstrated that the blockade of IL-6, CD47, and PD-L1 together could ameliorate pulmonary fibrosis by increasing phagocytosis of profibrotic fibroblasts and by eliminating suppressive effects on adaptive immunity." (PMID 36544757, 2022). "Its induction in mice drives lung fibrosis, which is abrogated by administration of anti-CD47." (PMID 32493933, 2020). "Although blocking antibodies against CD47 and IL-6 are relatively safe, clinical experience with PD-L1 inhibitors in cancer demonstrate severe pulmonary side effects potentially limiting their use and warranting caution in pulmonary fibrosis patients." (PMID 32493933, 2020). "Treatment with either a TSP-1 inhibitor or a CD47 inhibitor significantly attenuated BLM-induced ER stress and pulmonary fibrosis." (PMID 38136144, 2023). "Treatment with either TSP-1 inhibitor or CD47 inhibitor significantly attenuated BLM-induced ER stress and pulmonary fibrosis." (PMID 38136144, 2023). "Treatment with either LSKL or a CD47 inhibitor significantly attenuated BLM-induced ER stress and pulmonary fibrosis." (PMID 38136144, 2023). "In summary, we demonstrated that immune-checkpoint CD47, PD-L1 and IL-6 signaling was markedly upregulated in a JUN-dependent fashion in pulmonary fibrosis patients and mouse lung-fibrosis models." (PMID 32493933, 2020).
pulmonary fibrosis (continued). "Similarly, B6.129S2-Il6tm1Kopf/J (IL-6 knockout) mice treated with anti-CD47 antibody and the PD-1 blocking reagent HAC similarly resolved their lung fibrosis confirming synergistic antifibrotic efficacy of IL-6 and immune-checkpoint inhibition." (PMID 32493933, 2020).
T-cell acute lymphoblastic leukemia (9 papers, 2016 to 2025). Acute lymphoblastic leukemia of T-cell origin. "By targeting CD47, miR-708 has been identified as a promoter of phagocytosis in T-cell acute lymphoblastic leukemia, and miR-340 restoration boosts macrophage phagocytosis and improves T cell effector functions in PDAC." (PMID 41350707, 2025). "Here, we demonstrate that miR-708 regulates CD47, a transmembrane protein that inhibits phagocytosis in T cell acute lymphoblastic leukemia." (PMID 29368647, 2018). "Activation of CD47 triggers ICD in T-cell acute lymphoblastic leukemia." (PMID 38627685, 2024). "Moreover, MYC-mediated regulation of CD47 plays an important role in the initiation and development of T cell acute lymphoblastic leukaemia." (PMID 29050218, 2017).
cholangiocarcinoma (8 papers, 2020 to 2025). A carcinoma that arises from the intrahepatic biliary tree (intrahepatic cholangiocarcinoma) or from the junction, or adjacent to the junction, of the right and left hepatic ducts (hilar cholangiocarcinoma). "The effectiveness of CD47-SIRPα blockage in macrophage-mediated cholangiocarcinoma removal was also proven in vitro and in vivo." (PMID 35317832, 2022). "Attenuation of CD47-SIRPα signaling in cholangiocarcinoma promotes the phagocytotic potential of a variety of macrophage subpopulations and inhibits cholangiocarcinoma growth and intrahepatic metastasis." (PMID 32082311, 2020). "In cholangiocarcinoma, anti-CD47 treatment potentiates M1 and M2 phagocytosis." (PMID 36860925, 2023). "CD47 was also highly expressed in cholangiocarcinoma patients." (PMID 35317832, 2022). "It is worth noting that CD47 is also highly expressed in cholangiocarcinoma (CCA)." (PMID 40564180, 2025). "CD47 is frequently increased in HCC and strongly overexpressed in cholangiocarcinoma, where blockade of CD47/SIRP1a interaction enhanced phagocytosis and reduced tumor progression." (PMID 36845555, 2023). "In a study of CD47 expression in four cholangiocarcinoma (CCA) cell lines (KKU-100, KKU-055, KKU-213, and HuCCT1) and 54 CCA tissues samples, high expression of CD47 was found in 3 out of 4 of the CCAs cell lines (KKU-055, KKU-213, and HuCCT1) and in 50 out of 54 of the CCA tissue samples." (PMID 32082311, 2020).
Hypertension (8 papers, 2015 to 2025). The presence of chronic increased pressure in the systemic arterial system. "RET kinase inhibitors like pralsetinib and selpercatinib increase hypertension by upregulation of CD47 (integrin-associated protein), downregulation of cyclic guanosine monophosphate (cGMP), and reduction of nitric oxide (NO)." (PMID 36768635, 2023). "Taken together, the increase in CD47 seems to be responsible for the development of RET inhibitor-associated hypertension." (PMID 36768635, 2023). "Multivariate logistic regression analysis after adjustment with age, gender and BMI revealed a higher risk towards hypertension for the prevalent CD47 rs9879947AA homozygotes in HA hypertensive population." (PMID 34575042, 2021). "As reduced vasodilatation can cause hypertension, we performed a follow-up literature search using the search terms “CD47 hypertension”." (PMID 34698067, 2021). "Genotype-interactions between THBS1 rs2228263 and CD47 rs9879947 were relevant and the regression analysis highlighted the association of risk genotype-interactions with increased THBS1 levels in hypertension." (PMID 34575042, 2021). "According to this, systemic administrations of anti-CD47 mAbs for cancer treatment would probably lead to severe adverse events such as hypertension and thrombosis." (PMID 26578962, 2015). "With this model, we are able to investigate the unknown intracellular mechanisms of TSP1 via receptor CD47 and generate insight to help address the problem of systemic hypertension elicited by anti-angiogenic drugs, novel contributions of our work." (PMID 32357492, 2020). "Since CD47 is crucially involved in TSP1-mediated regulation of blood pressure, pharmaceutical targeting of the TSP1/CD47 mechanism may be useful for treatment of hypertension." (PMID 28714932, 2017). "Anti-CD47 mAbs could offer clear benefits in the treatment of cardiovascular diseases, however their use as anticancer drugs is likely to encounter the same limitations as bevacizumab, i.e., hypertension, thromboembolism, and tumor recurrence." (PMID 26578962, 2015). "The genetic analysis of THBS1, CD47 and THBS-CD family members highlighted their complex role in hypertension pathophysiology based on the population ethnicities or the environment." (PMID 34575042, 2021).
malaria (8 papers, 2016 to 2025). Malaria is a serious and sometimes fatal disease caused by a parasite that commonly infects a certain type of mosquito which feeds on humans. "The properties of erythroid precursors that accumulate in cd47−/− spleens are consistent with previous studies of stress induced extramedullary erythropoiesis associated with malaria or trypanosome infections." (PMID 37808833, 2024). "Therefore, understanding and targeting CD47‐SIRP‐α interaction could offer new therapeutic strategies for managing malaria and its associated symptoms." (PMID 41171200, 2025). "Overall, the interaction between CD47 on RBCs and SIRPα on macrophages is crucial in regulating erythrophagocytosis in malaria." (PMID 41171200, 2025). "Together, these findings suggesting that the administration of CD47 neutralizing antibody can result in a significant reduction of malaria parasites and apparently leading to faster infection control." (PMID 32882841, 2020). "Interestingly, since cancer cells often induce CD47 to evade immune eradication and malaria parasites infect young CD47-high RBCs to avoid clearance, targeting of the CD47–SIPRα axis is of high therapeutic interest." (PMID 34573346, 2021). "Therefore, suggesting an important role of CD47-SIRPa interaction in innate control of malaria." (PMID 32882841, 2020). "Parasites of the nonlethal strain of P. yoelii 17XNL were mostly detected infecting young RBCs expressing high levels of CD47, suggesting that malaria parasites could take advantage of negative signaling of CD47 to avoid early elimination by phagocytosis." (PMID 28018860, 2016).
myocardial infarction (8 papers, 2016 to 2025). Gross necrosis of the myocardium, as a result of interruption of the blood supply to the area, as in coronary thrombosis. "In human peripheral blood monocytes, the expression of CD47 protein in detergent-resistant membranes is linked to myocardial infarction and coronary artery disease in humans." (PMID 34418970, 2021). "The aim of this study was to investigate the effects of the GSK-3β/NF-κB pathway on integrin-associated protein (CD47) expression after myocardial infarction (MI) in rats." (PMID 34349643, 2021). "In this study, we introduced a biomimetic liposome as a nano‐degrader to degrade SIRPα on macrophage membrane and tested the effect on inhibition of CD47‐SIRPα immune checkpoint in myocardial infarction as the disease model." (PMID 38477522, 2024). "Herein, a biomimetic nano‐degrader is developed to inhibit CD47‐SIRPα axis in a site‐specific manner through SIRPα degradation, and its efficacy in acute myocardial infarction (AMI) is evaluated." (PMID 38477522, 2024). "In the myocardial infarction model, aRLP accumulated in the infarcted myocardium blocks CD47‐SIRPα axis and subsequently promoted the efferocytosis of apoptotic cardiomyocytes by macrophage, improved heart repair." (PMID 38477522, 2024). "In the myocardial injury-induced generation of apoptotic cells, anti-CD47 antibody treatment post-myocardial infarction improves inflammation resolution, reduces infarct size, and preserves cardiac function." (PMID 38473905, 2024). "Previous work has identified a role for CD47 in limiting blood flow and metabolism and has suggested additional benefits of therapeutic targeting of CD47 in myocardial infarction." (PMID 31827695, 2019). "Furthermore, the proteins CD47 and CD72, which are associated with integrin, exert an influence on the intercommunication between macrophages and cardiac myocytes after myocardial infarction (MI)." (PMID 37817547, 2023). "The investigation of alternative immune checkpoint targets, such as lymphocyte activation gene 3 (LAG-3) and CD47, has gained momentum as a potential strategy for cardiovascular protection, particularly after myocardial infarction (MI)." (PMID 41383640, 2025).
pancreatic ductal adenocarcinoma (8 papers, 2017 to 2025). An infiltrating adenocarcinoma that arises from the epithelial cells of the pancreas. "Appreciating that tumor-intrinsic characteristics play a significant role in dictating susceptibility to immunotherapy, we sought to investigate the synergy of NDV and CD47 blockade in a second cancer model of pancreatic ductal adenocarcinoma." (PMID 41322194, 2025). "In a pancreatic ductal adenocarcinoma model, EVs with the higher expression of CD47 had a longer half-life time in circulation than particles with lower CD47." (PMID 33105857, 2020). "However, CD47-blocking as a monotherapy shows limited anti-tumor effects in the pancreatic ductal adenocarcinoma (PDAC) model, which may be related to the limited phagocytosis of macrophages after CD47 blockade." (PMID 33224886, 2020).
Stroke (8 papers, 2016 to 2025). Sudden impairment of blood flow to a part of the brain due to occlusion or rupture of an artery to the brain. "Loss of proper CD47-SIRPα interactions has been shown to contribute to progression of neurodegenerative disease including stroke, AD, and MS." (PMID 39399501, 2024). "Some studies have also confirmed that in ischemic stroke, when CD47 is deficient, stroke can produce less edema, reduce the infiltration of neutrophils, and cause less secondary brain damage after focal cerebral ischemia, suggesting that CD47 can lead to neurovascular damage to some extent." (PMID 32733941, 2020). "Thus, TSP1 and CD47 are attractive therapeutic targets for antiaging therapy and the treatment of EC dysfunction-associated diseases, such as stroke and cancer." (PMID 27607583, 2016). "Such experimental results have advanced the premise that CD47 may possibly represent a potential anti-inflammatory target for the treatment of stroke." (PMID 34203368, 2021). "Therefore, the TSP-1/CD47 pathway may be a new target for the treatment of stroke." (PMID 32733941, 2020). "TSP-1/CD47 signal transduction can upregulate the expression of VEGF and MMP-9, thus leading to thrombosis and deterioration and accelerating stroke progression." (PMID 32733941, 2020). "Further research demonstrated that CD47 promotes MMP-9 (matrix metalloproteinase-9) and VEGR (Vascular endothelial growth factor) upregulation after stroke, which contributes to increased inflammatory cell infiltration and aggravated neuro-inflammation in the ischemic brain." (PMID 38125492, 2023).